RECK (reversion inducing cysteine rich protein with kazal motifs)
Diseases named in the same sentence as RECK in open-access papers (continued):
Sharing a sentence is not in itself a finding about the gene and the disease.
tumor (continued). "miRNA microarray analysis has revealed that miR-21 was dramatically elevated in HCC tumor cells, with significant reductions of the expressions of several tumor suppressor genes, including PTEN, PDCD4, RECK and TPM1 (PTEN)." (PMID 24112539, 2013). "Reversion-inducing cysteine-rich protein with Kazal motifs (RECK) protein is known to inhibit MMP-2 and MMP-9 activities and lead to strong suppression of invasion, metastasis, and tumor angiogenesis." (PMID 21573219, 2011). "In PICP-treated tumors the concurrent low expression of RECK and high expression of MMP-9, and the induction in tumor cells expression of MT1-MMP and MMP-2 will push up the balance of proteolysis compared to control." (PMID 19226458, 2009). "The results indicated that the ratios between MMP-2/RECK, MMP-9/RECK and MMP-14/RECK were significantly higher in the tumor than in adjacent non-tumor tissue samples (p = 0.0024, p = 0.0001 and p < 0.0001, respectively)." (PMID 19144199, 2009). "Additionally, MCPIP1 regulates the expression of the tumor suppressors PTEN, RECK and TIMP3 in cell lines and in in vivo models of ccRCC, indicating the importance of MCPIP1 expression in tumor development and progression." (PMID 39815326, 2025). "The correlation analysis illustrated that RECK was positively correlated with the stromal score, immune score, and estimate score; however, tumor purity exhibited a significantly negative relationship with RECK expression." (PMID 37904179, 2023). "Finally, when the CRISPR-Cas13a system was delivered by the CHAIN in vivo, it knocked down the targeted oncogene miR-21, restored PDCD4 and RECK, crippled downstream MMP-2, and eventually suppressed tumor growth." (PMID 37284454, 2023). "Because PD-L1 is significantly high in RECK-positive HCC, this event might reflect an immunogenic status in HCC with the recruitment of more tumor-infiltrating lymphocytes." (PMID 38139236, 2023). "Furthermore, direct immunoblot analysis of protein expression in lung tissue homogenates from wt mice demonstrates enhanced expression of RECK and decreased expression of MMP14 in rTIMP2-treated and tumor-free compared with vehicle control treated (HBSS) mice." (PMID 38234759, 2023). "In conclusion, we found that pancreatic RECK inactivation markedly promotes both spontaneous development of PDAC and its liver metastasis in the PDAC mouse models, establishing RECK as a bona fide tumor suppressor." (PMID 37712427, 2023). "The expressions of RECK and MMP9 were associated with tumor staging and grading, with a significant negative relationship between them." (PMID 35562926, 2022). "The miR-21 targets include the genespromoting apoptosis (PDCD4 and LRRFIP1), as well as the tumor suppressor genes inhibitinginvasion (RECK and TIMP3) and proliferation(IGFBP3).Furthermore, miR-21 can affect microglial behavior, thus ensuring favorableconditions for tumor growth." (PMID 34707896, 2021). "Since PD-L1 expression on tumor cells has been used widely as a predictive marker for efficacy of ICI therapy 33, to further analyze the relationship, the expression of RECK and PD-L1 in HCC tissues were assessed by immunohistochemistry staining of human HCC tissue microarray." (PMID 34093791, 2021). "Interestingly, RECK was first identified as a gelatinase inhibitor, reducing ECM breakdown and promoting angiogenesis in several tumor types, including colorectal, gastric, and HCC." (PMID 34745017, 2021). "Besides, animals injected with SiHa RECK+ and SW756 RECK+ displayed delayed tumor growth kinetics and, consequently, higher survival compared to controls." (PMID 34066355, 2021). "In conclusion, MAGI2-AS3 is an tumor suppressor in NSCLC and MAGI2-AS3 may sponge miR-25 to upregulate RECK, thereby promoting NSCLC invasion and migration." (PMID 32138716, 2020).
tumor (continued). "This study has not only experimentally validated the regulation of the expression of tumor-suppressive mRNAs such as HOXA5, MTSS1, PTEN, and RECK by MAGI2-AS3 in HGSC but also has suggested a network of how various pathways converge to aid in tumor suppression." (PMID 31842477, 2019). "In addition, miR-21-5p was controlled by one gene called miR-21 and in previous studies, miR-21 has been proved to be capable of targeting many tumor suppressors such as PTEN, RECK, BTG2 and TP63." (PMID 30134821, 2018). "Furthermore, the changes in RECK were more significant and pronounced relative to TIMP-2 indicating that it is a more reliable marker for tumour invasion." (PMID 28515436, 2017). "RECK is widely expressed in normal tissues and nonneoplastic cell lines, but its expression is frequently downregulated in several tumours and in fibroblasts transformed by various oncogenes." (PMID 28515436, 2017). "Previous work showed that miR-21 can promote tumor spread by upregulating the expression of phosphatase and tensin homolog (PTEN), programmed cell death 4 (PDCD4) protein, and reversion-inducing cysteine-rich protein with Kazal motifs (RECK)." (PMID 27793160, 2016). "Our data show that high RbAp46 expression was inversely correlated with low RECK expression in the tumor tissues compared to the adjacent non-tumor parts in all of 4 specimens analyzed (100%)." (PMID 25885317, 2015). "Besides miR-21, its target genes of PTEN, PDCD4, RECK were selected, including PTEN as one of the most important tumor suppressors." (PMID 26284486, 2015). "In contrast, RECK expression was markedly reduced in HCC tumors compared to corresponding adjacent nontumor tissues, and RECK staining was positive in approximately 34.7% (138 of 398) of nontumor sections and in 12.3% (49 of 398) of tumor areas." (PMID 26190376, 2015). "In several tissue models, RECK expression was shown to be inversely related to oncogenesis, being expressed in normal tissues but not in many tumor cell lines and tumor samples." (PMID 26449734, 2015). "RECK is a 110-kDa glycoprotein that is expressed in a number of normal tissues, however it is not expressed in transformed and tumor-derived cells." (PMID 24765174, 2014). "The restoration of RECK expression in malignant cells reduces pro-matrix MMP-9 secretion and suppresses the ability to invade and metastasize, suggesting a role for RECK in the regulation of MMPs and tumor invasiveness." (PMID 23833658, 2013). "In tumors in which RECK is absent or diminished, MMPs will be highly active, facilitating tumor promotion and progression." (PMID 22642976, 2012). "As previously noted, JJ012 is reported to have a consistent chromosome 9 monosomy, and this is significant given that a number of important tumour suppressor genes occupy this locus, including INK4A/ARF, PTCH1, and the more recently described RECK gene which is downregulated in many common cancers." (PMID 20584302, 2010). "One tumour suppressor with anti-angiogenic activity, via inhibition of gelatinases and possibly also via inhibition of VEGF, is reversion-inducing, cysteine-rich protein with kazal motifs (RECK)." (PMID 20584302, 2010). "Expression levels of the metalloproteinase inhibitor RECK were lower in all grades of tumour tissue than in normal tissue, but the relationship did not achieve statistical significance." (PMID 16465195, 2006). "Previous studies have shown that RECK is a membrane-anchored glycoprotein that binds and negatively regulates several MMPs, which proteolytically degrade extracellular matrix proteins, which is critical for tumor metastasis and invasion." (PMID 38612895, 2024). "Therefore, the overexpression of RECK had the capacity to modulate the expression of these proteins, including E-cadherin, N-cadherin, Vimentin and MMP2, thereby exerting inhibitory effects on the migration and invasion of tumor cells." (PMID 37904179, 2023).
tumor (continued). "This suggests that RECK suppresses cancer metastasis and recurrence rather than tumor growth." (PMID 37712427, 2023). "The downregulation of RECK expression might be one of the molecular mechanisms of CCA and HCC metastasis: when RECK is absent or diminished, MMPs are highly active, facilitating tumor growth and invasion." (PMID 38139236, 2023). "Moreover, we found that RECK+ tumors presented an increased number of double negative population and NK cells per 100,000 tumor cells than control tumors." (PMID 34066355, 2021). "We also found a negative correlation between RECK mRNA expression and tumor purity in HCC." (PMID 34093791, 2021). "This study for the first time highlights the tumor-suppressive role of LncRNA MAGI2-AS3 in HGSC and demonstrates its involvement in the regulation of miR-15b-5p, miR-374a-5p, and miR-374b-5p, and of their downstream mRNA targets (HOXA5, MTSS1, PTEN, and RECK) in HGSC cell lines." (PMID 31842477, 2019). "In addition, ECM degradation during tumor metastasis is controlled by other proteins, such as extracellular inducer of matrix metalloproteinase (EMMPRIN), reversion-inducing, cysteine-rich protein with Kazal motif (RECK) and tissue inhibitor of metalloproteinases (TIMPs)." (PMID 25116803, 2014). "Tumors with positive RECK expression had a lower incidence of HBV infection (p=0.008) and vascular invasion (p=0.040), and a better tumor differentiation (p=0.040) than tumors with negative RECK expression." (PMID 34093791, 2021). "The maximum separation between tissue types (normals, as opposed to tumour tissue plus cell lines) occurred with the transcript combination of MMP-7, RECK and SLC5A8." (PMID 19689820, 2009). "RECK, the matrix metalloproteinase (MMP) inhibitory protein, could potentially prevent tumor metastasis by controlling MMP activity in a negative manner." (PMID 39228402, 2024). "However, in non-tumor tissues, MAGI2-AS3 and RECK mRNA were not significantly correlated." (PMID 32138716, 2020).
cancer (100 papers, 2005 to 2026). A tumor composed of atypical neoplastic, often pleomorphic cells that invade other tissues. "Mir-181a-5p can promote the transformation of fibroblasts into cancer-associated fibroblasts that are pro-angiogenic through the miR-181a-5p/RECK axis, and it can facilitate the metastasis of CRC to the liver via extracellular vesicles." (PMID 38902711, 2024). "Recent reports implicated that the augmentation of the RECK expression can inhibit cancer cell invasion." (PMID 32349289, 2020). "This was particularly interesting since traditionally, RECK has been associated with pathological processes, specifically cancer where the expression of RECK has been observed to be reduced in several types of tumors." (PMID 26247610, 2015). "Numerous studies have reported that a lower expression of RECK is associated with a worse prognosis in a variety of cancers, but little is known with regard to the significance of RECK in PTCL." (PMID 23833658, 2013). "The reversion-inducing-cysteine-rich protein with Kazal motifs (RECK) down-regulation has been confirmed in numerous human cancers and is clinically associated with metastasis." (PMID 22428065, 2012). "The expression of six genes (RECK, SFRP2, UAP1L1, ACADL, ITR, and UGT3A1) is reported to be significantly correlated with methylation and relapse-free survival; the RECK gene is notable because of its association with the worst cancer prognoses." (PMID 22567014, 2012). "Recent studies have also shown that RECK methylation is associated with increase of metastasis and invasion in human cancers." (PMID 18665171, 2008). "Notably, the expression levels of RECK can predict the prognosis of various common cancers; lower RECK levels are often linked to increased invasiveness and a poorer prognosis." (PMID 39114567, 2024). "The results of GO, KEGG, and GSEA suggested that RECK might be involved in several crucial pathways underlying cancer progression, including MAPK signaling, Wnt signaling, apoptosis, DNA replication, and the cell cycle, as well as other functional pathways." (PMID 37904179, 2023). "The findings of this study indicate a strong association between RECK expression and the enriched cancer-related pathways, which may potentially contribute to the anticancer effects of RECK." (PMID 37904179, 2023). "RECK mutations, however, are rare in cancer genomes, suggesting that agents that re-activate dormant RECK may be of clinical value." (PMID 35149728, 2022). "RECK downregulation in cancer tissues is associated with a low survival rate and a poor prognosis because RECK inhibits angiogenesis, invasion, and metastasis in cancer via MMP inhibition." (PMID 24376819, 2013). "Indeed, RECK expression levels are predictive in determining prognoses in a number of common cancers; low levels of RECK are often associated with increased invasiveness and poor prognosis." (PMID 22642976, 2012). "Indeed, in many cancers RECK down-regulation is associated with high levels of MMP-9." (PMID 25432084, 2014). "RECK can also modulate the activity of the sheddases ADAM10 and ADAM17 which are involved in the shedding and activation of Notch, a functional link between RECK and CSCs cancer stem cells." (PMID 38139236, 2023). "In many types of cancer, the downregulation of RECK gene expression related to the expression and the activity of MMPs, such as MMP-2 and MMP-9, has been demonstrated." (PMID 38139236, 2023). "Pan-cancer analysis and meta-analysis of RECK expression from the Oncomine and TIMER2.0 platform yielded consistent results." (PMID 37904179, 2023). "In some RECK-downregulated cancer cell lines, restoration of RECK expression results in reduced invasion." (PMID 37712427, 2023). "In some RECK-downregulated cancer cell lines, restoring RECK expression results in reduced invasion and metastasis." (PMID 37712427, 2023).
cancer (continued). "RECK encodes a membrane-anchored protease-regulator which is often downregulated in a wide variety of cancers, and reduced RECK expression often correlates with poorer prognoses." (PMID 35149728, 2022). "RECK is downregulated in a wide variety of cancers, and reduced RECK expression often correlates with poorer prognoses." (PMID 35149728, 2022). "According to reports, RECK can reduce the invasion and migration of malignant tumors by abating MMP-9 secretion." (PMID 34790697, 2021). "RECK has also been shown to interact and inhibit other cellular pathways involved in cancer progression and metastasis, such as Notch and EGFR/RAS." (PMID 34745017, 2021). "Another candidate miRNA, miR-200c-3p which is at positions 126-132 and 1207-1214 of RECK 3′ UTR, has been investigated in several cancer types and is associated with cancer progression and metastasis by regulating epithelial–mesenchymal transition." (PMID 33987019, 2021). "Upregulation of miR-21 is common to most types of cancer and is implicated in the suppression of genes associated with cell growth and differentiation such as PDC4, RECK, TPM1 and PTEN." (PMID 34871435, 2021). "Some of these reported targets are cancer-related and are associated with carcinogenesis (such as SPRY2, SKY and SRSF3), cancer prognosis (such as CNOT6, RECK and GID4) or cancer cell plasticity (such as RMND5A)." (PMID 33804639, 2021). "This regulation of ECM components, combined with the observation that RECK is downregulated in cancers that metastasize, prompted several studies aimed at understanding RECK’s potential as a metastasis-suppressor." (PMID 34745017, 2021). "Down-regulation of RECK by oncogenic signaling leads to the excessive activation of MMPs, thereby promoting malignant behavior of cancer cells." (PMID 34093791, 2021). "Reduced RECK is a characteristic feature of many cancers, including HCC, promoting progression and metastasis." (PMID 34745017, 2021). "RECK, a gene involved in suppressing cancer cell migration, invasion, and metastasis, negatively regulates matrix metalloproteinase 9 (MMP9) by directly inhibiting its enzymatic activity and abolishing MMP9 secretion." (PMID 32051475, 2020). "In SMMC-7721 and Huh-7 HCC cell lines, overexpression of miR-135b markedly reduced the expression of the target proteins RECK and EVI5, of which only RECK had previously been shown to suppress migration of cancer cells." (PMID 32408596, 2020). "Among the target genes regulated by LINC01419, we focused on RECK because it is known to suppress tumors in various cancers, for example, HCC." (PMID 32522890, 2020). "RECK is known to be downregulated in human cancers resulting from transcription or epigenetic changes." (PMID 30733959, 2019). "RECK (reversion-inducing cysteine-rich protein with Kazal motifs) has important implications in cancer biology, especially in regulation matrix metalloproteinases (MMPs)." (PMID 30733959, 2019). "In the case of the RECK gene, it is frequently reported to be silenced through promoter methylation in a variety of human cancers." (PMID 29805750, 2018). "TSG restoration was found to inhibit tumor growth and reverse other cancer characteristics, therefore, we reasoned that restoration of RECK in human MPNST cells would inhibit cell growth." (PMID 29805750, 2018). "In fact, miR-21 up-regulation can change the biological process of cancer cells, including proliferation, apoptosis, and cellular invasion, probably via regulating RECK and PTEN as the main target genes." (PMID 29859516, 2018). "Previous studies have reported that a high expression of miR-590-5p regulates RECK and AKT/ERK expression to induce chemoresistance and that its abnormal expression is highly associated with poor prognosis, metastasis and cancer cell proliferation." (PMID 29549343, 2018). "Low RECK expression is strongly associated with high expression of MMP-2 and MMP-9 in different types of cancers." (PMID 28134767, 2017).